ITGB1 (integrin subunit beta 1)
Diseases named in the same sentence as ITGB1 in open-access papers (continued):
Sharing a sentence is not in itself a finding about the gene and the disease.
head and neck cancer (6 papers, 2021 to 2025). A primary or metastatic malignant neoplasm affecting the head and neck. "Targeted suppression of ITGB1 increased the susceptibility of cancer cells to chemotherapeutic drugs in head and neck cancer." (PMID 38279122, 2024). "Tumor cells grown on 3-d laminin-rich ECM cultures were radiosensitive to dual-targeted treatment with AIIB2 (targeting ITGB1)/imatinib (targeting c-Abl, a tyrosine kinase), which also significantly reduced DNA damage repair in head and neck cancer cells." (PMID 38279122, 2024). "The simultaneous targeting of ITGB1 and EGFR also produced radio-sensitizing effects on head and neck cancer, aIIB2 increased cytotoxicity and radio-sensitization in a variety of head and neck cancer cells when combined with cetuximab and X-rays." (PMID 38279122, 2024).
liver fibrosis (6 papers, 2012 to 2025). "ITGB1 has been shown to be a key regulator of fibrosis in patients with hepatitis B virus-associated liver fibrosis (HBV-LF) by analyzing the genetic profile of these patients." (PMID 37808522, 2023). "Parallel studies have also confirmed that MMP14 and ITGB1 are upregulated in hepatic fibrosis, which is gradually reduced with recovery suggesting that their blocking could be a potential anti-inflammatory therapeutic strategy in NASH." (PMID 36077546, 2022). "The mRNAs of liver fibrosis factors, such as α-SMA, Col1a1, platelet-derived growth factor receptor (PDGFR)-β, TGF-β1, fibronectin (FN) 1, discoidin domain receptor (DDR) 2, and β1 integrin (ITGB1), were upregulated in the livers of MCDD-fed mice compared to MCCD-fed mice B." (PMID 22849305, 2012).
lymphoma (6 papers, 2007 to 2022). A malignant (clonal) proliferation of B- lymphocytes or T- lymphocytes which involves the lymph nodes, bone marrow and/or extranodal sites. "In the CSF + LM (lymphoma) vs. CSF − LM comparison, ITGB1, IL6, ABL1, CYCS, among others, were differentially observed and expressed in cancer cells." (PMID 35053611, 2022).
metastatic tumors (6 papers, 2014 to 2025). "The immunoblots of cells, as well as immunohistochemistry (IHC) of tumor xenografts, consistently demonstrated an increased expression of the heterophilic adhesion molecule integrin β1 (ITGB1) in metastatic tumors compared to non-metastatic tumors." (PMID 28721370, 2015). "Among them, ITGB1, TWIST1 and KRT6B are consistently up-regulated in metastatic tumors of both MB49 sub-clones." (PMID 31092844, 2019).
pancreatic ductal adenocarcinoma (6 papers, 2018 to 2025). An infiltrating adenocarcinoma that arises from the epithelial cells of the pancreas. "Also, increased ITGB1 expression was confirmed to be associated with poor prognosis and increased fibroblast infiltration in pancreatic ductal adenocarcinoma." (PMID 37733241, 2023). "Our previous study of pancreatic ductal adenocarcinoma (PDAC) cells showed that aberrant expression of ITGA3 and ITGB1 (genes for two integrins that form homodimers) was significantly associated with poor prognosis of patients with PDAC." (PMID 34199886, 2021).
COVID-19 (5 papers, 2022 to 2025). A disease caused by infection with severe acute respiratory syndrome coronavirus 2. "All the hub genes with the exception of ITGB1 were downregulated at 12 weeks in patients that experienced critical COVID-19 in the acute phase of the disease." (PMID 41141600, 2025).
myeloma (5 papers, 2019 to 2024). "Gene ITGA4 along with ITGB1 codes for integrin VLA4 that mediates homing of myeloma cells into bone marrow and augment IL6 in the microenvironment." (PMID 34040057, 2021).
Myocardial fibrosis (5 papers, 2023 to 2026). "To validate the role of Itgb1 in the heart in myocardial fibrosis during diabetes, we used the adeno-associated virus 9 (AAV9) to deliver Itgb1 siRNA, which preferentially targets the heart." (PMID 37010266, 2023). "Collectively, these data reveal that collagen histaminylation limits TGM2-dependent crosslinking, softens the extracellular matrix, and inhibits the PIEZO1/ITGB1 axis, thereby mitigating myocardial fibrosis after AMI." (PMID 42270610, 2026). "Some study shows that the cardiomyocyte-specific knockdown of ITGB1 leads to the development of myocardial fibrosis and heart failure." (PMID 36604692, 2023). "Taken together, our results show that Itgb1 in Hrchi fibroblasts contributes to HFD/STZ-induced myocardial fibrosis." (PMID 37010266, 2023). "It is therefore reasonable to surmise that the interaction between Itgb1 and its cognate ligand is involved in diabetes-related myocardial fibrosis." (PMID 37010266, 2023). "Perhaps, the gain-of-function of the Lgals3bp–Itgb1 and Fn1–Itgb1 pairs may explain the role of Hrchi fibroblasts in diabetic myocardial fibrosis." (PMID 37010266, 2023). "Although the role of these candidate hub genes has been well established in myocardial fibrosis, the function of Itgb1 is currently unknown." (PMID 37010266, 2023). "Finally, we validated the role of the Itgb1 hub gene-mediated intercellular communication drivers of diabetic myocardial fibrosis in Hrchi fibroblasts, and confirmed the results through AAV9-mediated Itgb1 knockdown in the heart of diabetic mice." (PMID 37010266, 2023).
oral squamous cell carcinoma (5 papers, 2020 to 2024). "In another study, miR-124 was found to suppress oral squamous cell carcinoma motility by targeting integrin subunit beta 1 (ITGB1)." (PMID 33806361, 2021). "miR-124-3p regulates cell cycle by targeting integrin subunit beta 1 (ITGB1) in oral squamous cell carcinoma cells, suggesting that miR-124-3p expression might remain at lower levels during normal palate development." (PMID 34178974, 2021).
renal cell carcinoma (5 papers, 2018 to 2023). "And ITGB1 Upregulation promotes the development and metastasis of renal cell carcinoma." (PMID 34722263, 2021). "Furthermore, miR-134 is known as a tumor suppressor because it directly silences the KRAS oncogene as well as the integrin beta 1 (ITGB1) oncogene, the activity of which genes also promotes malignant transformation and proliferation of malignant cells, which can lead to renal cell carcinoma (RCC)." (PMID 33539381, 2021). "The study performed on renal cell carcinoma showed that the JAM3 gene is critical for its tumor migration ability via the regulation of genes coding for N-cadherin, integrin β1 (ITGB1) and MMP2." (PMID 35742950, 2022).
Stroke (5 papers, 2022 to 2024). Sudden impairment of blood flow to a part of the brain due to occlusion or rupture of an artery to the brain. "It has been reported that Itgb1, which is also in the integrin family, promotes oligodendrocyte regeneration and myelin regeneration in the chronic phase of stroke by affecting the phenotype of microglia." (PMID 37063847, 2023). "In murine stroke model, brain Tregs secrete osteopontin (SPP1) to promote tissue-regenerative microglial reactions for brain repair through the Integrin beta-1 (ITGB1) receptor, expressed on microglia." (PMID 35844606, 2022). "Similarly, genes involved in integrin cell surface interactions including Itga10, Itgb3, Vcam1, Itgb1, Itgae, Itgb7, Itga1, Itga5, Icam1, Itgb2, Pecam1, and Icam2 were depleted in male MMP-3 KO stroke brains." (PMID 39000490, 2024).
chordoma (4 papers, 2023 to 2025). Chordomas are rare malignant tumors arising from embryonic remnants of the notochord in axial skeleton. "ITGB1 plays a role in promoting chordoma progression by binding to GMFG produced by ERS-CAFs, thereby enhancing tumor malignancy." (PMID 40909272, 2025). "Hypoxic microenvironment reprogramed CAFs into ERS-CAF subtype, which can regulates SPP1macrophage to aggravate chordoma progression via the IER2/GMFG/ITGB1 axis in chordoma." (PMID 41425545, 2025). "Taking together, these outcomes suggested that ERS‐CAF‐derived GMFG drove chordoma malignant progression through its interaction with ITGB1 on tumor cells." (PMID 39207055, 2024). "GMFG produced by ERS‐CAF mediated the formation of an inhibitory immune microenvironment to promote tumor cell proliferation, migration, and invasion by binding to ITGB1 on tumor cells, ultimately leading to chordoma progression." (PMID 39207055, 2024). "IER2 stimulated GMFG factor secretion by ERS‐CAF, which then promoted chordoma malignant progression through binding with ITGB1 on tumor cells." (PMID 39207055, 2024). "To clarify the regulatory role of the GMFG/ITGB1 signaling axis in chordoma progression, we introduced exogenous GMFG to the CAF medium." (PMID 39207055, 2024). "To delve into the biological behavior regulated by the GMFG/ITGB1 axis that affected the progression of chordoma, we first reanalyzed the bulk RNA‐seq data (n = 126)." (PMID 39207055, 2024). "To examine the clinical significance ITGB1 in chordoma, we assessed the relationship between their expression and patient outcomes using bulk RNA‐seq data involving 126 tumor samples." (PMID 39207055, 2024). "GMFG secreted by ERS‐CAF reshapes the immune microenvironment possibly via recruiting SPP1+ macrophages to promote chordoma progression by binding to ITGB1 on tumor cells." (PMID 39207055, 2024). "The paracrine GMFG signaling from ERS‐CAF promoted tumor cell proliferation, migration, and invasion via binding with ITGB1 on tumor cell, thereby driving chordoma progression." (PMID 39207055, 2024). "Our analysis revealed that the interaction between FN1 and CD44, as well as the interaction between FN1 and ITGA4/ITGB1, plays prominent roles in the communication network of both primary and recurrent chordomas." (PMID 37784253, 2023). "Collectively, the findings suggest that ERS‐CAF regulates SPP1+ macrophage to aggravate chordoma progression via the IER2/GMFG/ITGB1 axis, which may be targeted therapeutically in future." (PMID 39207055, 2024). "Collectively, these data suggest that ITGB1 on tumor cells might likely expedite chordoma progression by inducing an inhibitory immune microenvironment through recruiting SPP1+ TAMs, although the precise molecular mechanisms deserve further exploration." (PMID 39207055, 2024). "Moreover, we identified a significant positive correlation between GMFG and ITGB1 expression based on the bulk RNA‐seq data from 126 chordoma samples." (PMID 39207055, 2024). "Additionally, we conducted correlation analysis between ITGB1 and GMFG using two chordoma bulk RNA‐seq datasets (GSE239531 and GSE205457) from the GEO database as well as RNA‐seq data involving 42 bone tumor cell lines from the CCLE database." (PMID 39207055, 2024). "Interestingly, in recurrent chordomas, interactions involving FN1 and ITGAV/ITGB1, as well as FN1 and ITGA3/ITGB1, emerged as significant contributors to this communication network." (PMID 37784253, 2023). "The exact mechanisms of how the GMFG/ITGB1 signaling influences chordoma biology is not known." (PMID 39207055, 2024).
esophageal cancer (4 papers, 2017 to 2025). A primary or metastatic malignant neoplasm involving the esophagus. "In addition, it has been previously found that overexpression of ITGB1 may be associated with chemoresistance in esophageal cancer." (PMID 38402311, 2024). "Targeting ITGB1, especially in patients treated with docetaxel, may enhance the efficacy of chemotherapy in patients with esophageal cancer." (PMID 38402311, 2024).
esophageal squamous cell carcinoma (4 papers, 2020 to 2024). Esophageal squamous cell carcinoma (ESCC) is a type of esophageal carcinoma (EC) that can affect any part of the esophagus, but is usually located in the upper or middle third. "Depletion of integrin subunit beta 1 (ITGB1) enhanced the sensitivity of tumor cells to docetaxel in esophageal squamous cell carcinoma." (PMID 32232000, 2020). "In esophageal squamous cell carcinoma (ESCC), ZNF750 suppresses ITGB1 transcription while SIPA1 inhibits the ITGB1 expression." (PMID 38279122, 2024).
gastric tumor (4 papers, 2019 to 2024). "Thirdly, we provided a new strategy to reverse the drug resistance induced by TICs, in which ITGB1/NF-κB inhibitors combined with chemotherapy exhibited superior tumor suppressive effects in gastric tumor models." (PMID 34758833, 2021). "Subsequently, we further assessed the expression of type I collagen and ITGB1 in those chemo-resistant gastric tumor tissues." (PMID 34319913, 2021). "Lastly, the expression of ITGB1 was detected in gastric tumor tissues from clinical patient by immunohistochemistry, in which tumor tissues from high stage patients (n = 10, stage T3–T4) revealed elevated ITGB1 expression compared to the low stage group (n = 10, stage T1–T2)." (PMID 34758833, 2021).
medulloblastoma (4 papers, 2015 to 2022). A malignant, invasive embryonal neoplasm arising from the cerebellum. "Our findings showed that miR-192-mediated inhibition of ITGB1 expression results in decreased cell anchoring ability during the leptomeningeal dissemination of medulloblastoma." (PMID 26506238, 2015). "Compared to the normal cerebellum, the expression level of miR-192 in medulloblastoma cells is lower, and studies indicated that miR-192 suppresses the expressions of ITGAV, ITGB1, ITGB3, and CD47 in medulloblastoma." (PMID 35464451, 2022). "In medulloblastoma, miR-192 has been described as a suppressor of metastasis and inhibitor of cell adhesion to ECM components via integrins such as ITGB1 and ITGAV." (PMID 30473751, 2018). "After miR-192 transfection, there was a significant reduction in ITGAV, ITGB1, ITGB3, and CD47 in all miR-192-transfected medulloblastoma cells in comparison with NC miR-transfected cells (all P values <0.05)." (PMID 26506238, 2015). "In summary, this study revealed that the loss of miR-192 expression exerts wide ranging effects on cell proliferation and cell anchoring by activating DHFR and by molecular cross talk between ITGAV, ITGB1, ITGB3, and CD47 in the leptomeningeal dissemination of medulloblastoma." (PMID 26506238, 2015).
myocardial ischemia (4 papers, 2017 to 2024). A disorder of cardiac function caused by insufficient blood flow to the muscle tissue of the heart. "Existing research has found that ITGB1 is involved in cardiac remodeling post-MI, which is essential for cardiac adaptation to myocardial ischemia and the prevention of AMI." (PMID 39062199, 2024). "Endothelial ITGB1 (β1 integrin) is essential for the heart to adapt cardiac ischemia and protects from myocardial infarction." (PMID 36248430, 2022). "Transient episodes of myocardial ischemia promote the proliferation of endothelial cells and the formation of small arteries throughout the myocardium in response to the myocardial infarction, where the ITGB1 is involved." (PMID 36604692, 2023).
neuroblastoma (4 papers, 2020 to 2021). Neuroblastoma (NB) is the most common solid, extracranial childhood tumor. "In addition to its predicted targeting of MYH9, miR-124-3p was predicted to target additional cytoskeletal genes (PLEC, ITGB1, VIM, and ACTN4) from our panel, which were overexpressed in the resistant SK-N-ASCis24 neuroblastoma cell model." (PMID 33330445, 2020). "These cytoskeletal genes (MYH9, PLEC, ITGB1) and mesenchymal markers (VIM, ACTN4), were previously reported by our lab to be up-regulated with cisplatin resistance development and involved in phenotypic and morphological modulation observed in our neuroblastoma cell model." (PMID 33330445, 2020). "The cytoskeletal genes MYH9, PLEC, ITGB1, VIM, and ACTN4, were previously reported by our lab to drive EMT-like morphological transformation and increased invasiveness (2.5 fold) in the MES SK-N-ASCis24 neuroblastoma cell line, coinciding with resistance development." (PMID 33330445, 2020).
oral cancer (4 papers, 2015 to 2024). "Similarly, in oral tumors, ITGB1 expression is increased in oral cancer stem cells, and upregulation of ITGB1 in oral cancer stem cells leads to increased expression of other stemness markers and an increase in the size of stem cell spheres." (PMID 39239559, 2024).
pancreatic adenocarcinoma (4 papers, 2012 to 2025). "Our results also show that high expression of the fibronectin receptor subunits ITGA5 and ITGB1 correlates with poor disease-free survival in patients with pancreatic adenocarcinoma." (PMID 37563605, 2023).
psoriasis (4 papers, 2010 to 2024). An autoimmune condition characterized by red, well-delineated plaques with silvery scales that are usually on the extensor surfaces and scalp. "However, in wound healing and in several cutaneous diseases such as psoriasis and lichen planus, ITGB1 expression is maintained in keratinocytes of the subrabasal layer, causing these cells to remain proliferative and to disturb terminal differentiation." (PMID 22590584, 2012).
small cell lung carcinoma (4 papers, 2014 to 2021). Small cell lung cancer (SCLC) is a highly aggressive malignant neoplasm, accounting for 10-15% of lung cancer cases, characterized byrapid growth, and early metastasis. "For example, we have found that the CRL5–SOCS3 complex degrades ITGB1 to inhibit small cell lung cancer cell migration and metastasis, and the CRL5–SOCS6 complex governs Sin1 level and limits mTORC2 function." (PMID 34164402, 2021). "Further, genes in the EGFR/ITGB1-T4R differential network are connected with various cancers, including prostate, and small cell lung cancer, suggesting that despite phenotypic reversion to normal, some malignant genes remain active in the EGFR/ITGB1-T4R cells." (PMID 25057922, 2014).
thyroid cancer (4 papers, 2018 to 2024). "Other cell types such as FTC-133 thyroid cancer cells and mesenchymal stromal cells showed a reduced ITGB1 gene expression when they were exposed to space or s-μg conditions, whereas the ITGB1 mRNA was up-regulated in chondrocytes." (PMID 36674696, 2023). "PLA2R1 competed with FN1 to bind ITGB1 to mediate extracellular matrix remodeling and thereby inhibit thyroid cancer progression." (PMID 37345058, 2023). "In short, PLA2R1 knockdown promotes the tumorigenesis and proliferation of thyroid cancer via the FN1-mediated ITGB1/FAK axis in vivo." (PMID 37345058, 2023). "In this list, we found that hsa-mir-507 has a corresponding protein complex, corum-1422, and hsa-mir-221-222 cluster regulates nine protein complexes, of which ITGB1, ITGB3 and CD47 were associated with the thyroid cancer." (PMID 29351231, 2018). "Our analysis found that the expression level of ITGB1 in thyroid tumors was considerably correlated with polymer methylation, suggesting that ITGB1 could have a very important role in the progression and prognosis of thyroid cancer." (PMID 38402311, 2024). "In addition, according to the results of Co-IP, FN1 expression was negatively correlated with PLA2R1 expression and positively correlated with ITGB1 expression in thyroid cancer." (PMID 37345058, 2023). "FN1 may function in thyroid cancer cells by interacting with ITGB1 and then activating the FAK signaling pathway." (PMID 37345058, 2023). "This suggests that ITGB1 may be a potential marker for thyroid cancer proliferation and metastasis." (PMID 38402311, 2024). "By attenuating the interaction of FN1 with ITGB1, overexpressed PLA2R1 suppresses the activation of the downstream FAK-signaling pathway, which in turn influences the malignant proliferation of thyroid cancer cells." (PMID 37345058, 2023). "Therefore, we hypothesized that the overexpressed PLA2R1 competes with FN1 to bind ITGB1 and inhibit the activation of the downstream FAK-signaling pathway by attenuating the interaction between FN1 and ITGB1, thereby affecting the malignant proliferation of thyroid cancer cells." (PMID 37345058, 2023).
viral infection (4 papers, 2023 to 2025). "Integrin β1 (ITGB1), a transmembrane cell adhesion molecule, is present in various cells and mediates numerous viral infections." (PMID 38255903, 2024). "Conversely, viral infection did not alter the expression of genes encoding adhesion molecules, such as GJA1 and ITGB1, unlike what was observed upon infection at higher MOI (0.5)." (PMID 37569398, 2023).